SIPA1L2 (signal induced proliferation associated 1 like 2)
Synonyms: KIAA1389; SPAR2; SPAL2
Tractability: PROTAC: ubiquitination databases record sites on it; its protein half-life has been measured.
Gene: Protein-coding gene on chromosome 1 (232,397,622 to 232,631,404, reverse strand). Ensembl gene ENSG00000116991.
Subcellular location (Human Protein Atlas): Nuclear bodies; Nuclear membrane; Nucleoplasm; Golgi apparatus
Gene Ontology:
Molecular function: protein binding; GTPase activator activity
Biological process: regulation of small GTPase mediated signal transduction
Cellular component: glutamatergic synapse
Genetic constraint (gnomAD): Loss-of-function variants: 55 observed, 167.24 expected, observed/expected ratio (o/e) 0.33, 90% interval 0.26 to 0.41. The upper end of that interval is the gene's LOEUF score, 0.41, which puts it in group 1 of 6, group 1 being the genes least tolerant of losing a copy. Missense variants: 1,974 observed, 2,281.6 expected, observed/expected ratio (o/e) 0.87, 90% interval 0.83 to 0.9. Synonymous variants: 877 observed, 906 expected, observed/expected ratio (o/e) 0.97, 90% interval 0.92 to 1.02.
Homologues: Orthologues: chimpanzee SIPA1L2 (99% identical), rabbit SIPA1L2 (97% identical), macaque SIPA1L2 (95% identical), dog SIPA1L2 (95% identical), pig SIPA1L2 (92% identical), guinea pig SIPA1L2 (92% identical), rat Sipa1l2 (92% identical), mouse Sipa1l2 (91% identical), tropical clawed frog sipa1l2 (65% identical), zebrafish sipa1l2 (60% identical), Drosophila melanogaster RapGAP1 (13% identical), Caenorhabditis elegans F53A10.2 (11% identical). Paralogues in human: SIPA1L1 (54% identical), SIPA1L3 (46% identical), SIPA1 (26% identical), GARNL3 (15% identical), RAP1GAP2 (13% identical), RAP1GAP (13% identical).
Diseases named in the same sentence as SIPA1L2 in open-access papers:
SIPA1L2 is named in the same sentence as 17 diseases in open-access papers, as found by Europe PMC text mining. Sharing a sentence is not in itself a finding about the gene and the disease. The quoted sentences say what the papers report.
atherosclerosis (1 paper, 2025). A disease characterized by the build-up of fatty material and calcium deposition in the arterial wall resulting in partial or complete occlusion of the arterial lumen. "Endothelial colony-forming cells are ECs that mediate vascular repair and secrete exosomes containing miR-21-5p in atherosclerosis; these exosomes deliver miR-21-5p to target signal induced proliferation associated 1 like 2 (SIPA1L2) that interacts with LC3 and rescues autophagy in the ECs." (PMID 40823532, 2025).
COVID-19 (1 paper, 2021). A disease caused by infection with severe acute respiratory syndrome coronavirus 2. "Seven of our significant genes higher (GALNT14, OAS1, CCRL2, OAS3, CCR1, OAS2, SIPA1L2) in COVID-19 and two lower (HLA-DPB1, HLA-DQA2) were identified to overlap." (PMID 34335605, 2021).
kidney cancer (1 paper, 2019). Primary or metastatic malignant neoplasm involving the kidney. "In contrast, our study enabled prioritizing 138 genes based on a refined set of putative somatic SNVs, where 49 of those genes had previously been related to kidney cancer according to the literature, and two genes (SIPA1L2 and EIF3A) were validated in independent datasets from TCGA." (PMID 31156702, 2019).
Obesity (1 paper, 2025). Accumulation of substantial excess body fat. "In particular, rs6424242 is located in an upstream region of the SIPA1L2 gene, which has been previously linked to obesity-related traits, response to alcohol consumption, and neuroticism based on Open Targets and the GWAS Catalog." (PMID 40830362, 2025).
renal carcinoma (1 paper, 2019). A carcinoma arising from the epithelium of the renal parenchyma or the renal pelvis. "SIPA1L2 is a renal cancer biomarker according to The Human Protein Atlas4, as its expression associates with a significant unfavorable prognosis." (PMID 31156702, 2019).
Sepsis (1 paper, 2025). Sepsis is defined as life-threatening organ dysfunction caused by a dysregulated host response to infection. "Conversely, the expression of CCNB2, HJURP, KREMEN1, LILRA5, and SIPA1L2 was significantly higher in the sepsis group (P < 0.05)." (PMID 40129981, 2025).
cancer (3 papers, 2010 to 2020). A tumor composed of atypical neoplastic, often pleomorphic cells that invade other tissues. "The dysregulation of SIPA1L2 is also known as a risk factor for cancer." (PMID 33343635, 2020). "Two EG pairs containing the target genes SIPA1L2 (signal-induced proliferation-associated 1 like 2) and LOC642852 showed a significant correlation in 23 cancers." (PMID 33343635, 2020).
infection (1 paper, 2023). The state of being infected such as from the introduction of a foreign agent such as serum, vaccine, antigenic substance or organism. "The expression of C6, C7, IRAK4, LBP, and RIPK2 was significantly upregulated after infection with A. hydrophila, while the expression of SIPA1L2 and NFATC1 was significantly downregulated after infection." (PMID 36910190, 2023).
SIPA1L2 also shares sentences with these, for which no sentence is quoted: Alzheimer disease (1 paper); amyotrophic lateral sclerosis (1); aortic stenosis (1); astrocytomas (1); diabetes (1); Parkinson disease (1); psychiatric disorder (1); schizophrenia (1); systemic lupus erythematosus (1).